CLCN7 (Cl-/H+ antiporter 7)
Diseases named in the same sentence as CLCN7 in open-access papers (continued):
Sharing a sentence is not in itself a finding about the gene and the disease.
Yunis-Varón syndrome (1 paper, 2023). "Reduction of CLCN7 provides a new target for treatment of FIG4 and VAC14 deficiencies that lack specific therapies, such as Charcot-Marie-Tooth Type 4J and Yunis-Varón syndrome." (PMID 37363915, 2023).
ZIKV infection (1 paper, 2022). "ZIKV infection significantly upregulated genes related to lysosomal biosynthesis, including LAMP1 and CLCN7 (lysosomal transmembrane proteins); CSTB and CSTD (lysosomal hydrolases); and ATP6V1C1 and ATP6V0D1 (v-ATPase proteins)." (PMID 36405969, 2022).
cancer (3 papers, 2020 to 2024). A tumor composed of atypical neoplastic, often pleomorphic cells that invade other tissues. "Future research should investigate whether and how mTOR signaling impacts the ClC-b/CLCN7 and NF-κB pathways in macrophage-mediated phagocytosis of cancer cells." (PMID 39766137, 2024).
bone disorder (2 papers, 2019 to 2022). "Autosomal dominant osteopetrosis II (ADO II, MIM166600) is a sclerosing bone disorder caused by CLCN7 mutation." (PMID 35370969, 2022). "Eight of these patients received a genetic diagnosis of CLCN7 mutations and were re-examined, in this study, for any clinical manifestations consistent with an extra-skeletal disease." (PMID 31231577, 2019).
skeletal dysplasia (2 papers, 2019 to 2023). Any Mendelian diseases that affects growth and development of the skeleton. "In this work, we have tested this strategy in vivo with the aim to generate two conditional knock-in mice for missense mutations in the Impad1 and Clcn7 genes causing two different skeletal dysplasias." (PMID 30865697, 2019).
CLCN7 also shares sentences with these, for which no sentence is quoted: lysosomal storage disease (12 papers); albinism (3); neurodegenerative disease (3); neurological disorders (3); Bartter syndrome (2); Blindness (2); Dent disease (2); genetic disease (2); Myotonia (2); Myotonia congenita (2); Retinal atrophy (2); tumor (2); Alzheimer disease (1); Anxiety (1); B-cell non-Hodgkin lymphoma (1); Brain atrophy (1); cardiomyopathy (1); channelopathies (1); craniometaphyseal dysplasia (1); Danon disease (1); depression (1); developmental delay (1); diaphyseal dysplasia (1); dilated cardiomyopathy (1); dysplasia (1); frontometaphyseal dysplasia (1); Gaucher disease (1); hearing loss (1); Hydrocephalus (1); hyperaldosteronism (1).
A further 29 diseases each share a sentence with CLCN7 in 1 paper.